SIRT7 (sirtuin 7)
Diseases named in the same sentence as SIRT7 in open-access papers (continued):
Sharing a sentence is not in itself a finding about the gene and the disease.
breast carcinoma (continued). "Together, the data implicates that SIRT7 antagonizes TGF-β signaling-regulated EMT and breast cancer invasive ability." (PMID 28827661, 2017). "Together, the data suggest SIRT7 against SMAD4 stability as a potential therapeutic target for lung metastasis and beneficial effects of resveratrol in breast cancer treatment." (PMID 28827661, 2017). "Further, protein levels of SIRT7 and SMAD4 were examined in a human breast cancer tissue array by immunohistochemistry microscopy." (PMID 28827661, 2017). "Furthermore, the natural product kaempferol inhibited SIRT7 expression and upregulated the MCM6‐Kcr levels, effectively improving the sensitivity of breast cancer cells to chemotherapeutic treatments." (PMID 39477811, 2025). "SIRT7 interacts with EST1 and its co-binding to the TEK promoter leads to H3K18ac deacetylation to inhibit its expression, which inhibits invasion and metastasis of breast cancer cells." (PMID 39479446, 2024). "First, considering the reported interactions between SIRT7, FKBP51, and AKT in breast cancer 42, we hypothesize that ACAT1 may regulate the activity of AKT by acetylating a certain kinase and regulating its ability to phosphorylate AKT." (PMID 38817856, 2024). "In this study, we found that the expression of γH2AX, a marker of CIN, was significantly increased in the DOX treatment group, which was accompanied by the downregulated expression of SIRT7, simultaneous indication inhibits of SIRT7 expression and enhancement of CIN in breast cancer cells." (PMID 37056924, 2023). "We further investigated the relationship between SIRT7, LAP2α, and CIN in breast cancer." (PMID 37056924, 2023). "Mechanistically, we established a causal link between SIRT7 downregulation and enhanced CIN in DOX-treated cells, in which SIRT7 interacted directly with LAP2α to promote its ubiquitination and degradation and to regulate CIN and metastasis of breast cancer cells." (PMID 37056924, 2023). "Additionally, the authors corroborated their findings with knockout experiments, in which SIRT7 knockout with either shSIRT7 or siSIRT7 activated TGF-β signaling to promote EMT-related gene transcription and lung metastasis of breast cancer." (PMID 36291902, 2022). "Also, overexpression of SIRT7 in response to downregulation of miR-3666 has been observed in NSCLC and breast cancer cells." (PMID 35087589, 2022). "Furthermore, a recent study demonstrated that SIRT7 antagonizes TGF-β signaling and inhibits metastasis of breast cancer." (PMID 36291902, 2022). "On the contrary, a more recent study revealed that SIRT7 promotes Adriamycin-induced metastasis in breast cancer by interacting with TIE2, a tyrosine kinase receptor that induced the dormancy of breast cancer cells, resulting in increased resistance to chemotherapy." (PMID 36291902, 2022). "The findings can inspire that RES selectively targets SIRT7 and PI3K in breast cancer metastasis, which might provide new strategy for the treatment." (PMID 33937049, 2021). "The results found that SIRT7 promoted the degradation of SMAD4, which is the key factor in TGF-β pathway, which indicated the potential of the therapeutic target for SMAD4-mediated breast cancer." (PMID 33193750, 2020). "Together, the data provide in vivo and clinical evidences supporting a negative correlation between SIRT7 and breast cancer lung metastasis." (PMID 28827661, 2017). "Apparently, SIRT7 favors the development of breast cancer but not the development of metastasis." (PMID 35585284, 2022). "Sirt7 is high expressed in breast cancer, which is an indicator of poor prognosis, and the expression of Sirt7 is positively correlated with the expression of IRF5 and PD1, which increases M1 macrophages, and depletes T cells in the immune environment of breast cancer." (PMID 34880761, 2021).
breast carcinoma (continued). "Moreover, PyMT;Sirt7-TG mammary tumors showed much lower AKT activity, again supporting the hypothesis that SIRT7 inhibits AKT activation." (PMID 34433808, 2021). "In addition, we used the antibody HPA053669 of SIRT7 to analyze the immunohistochemical results of normal and tumor tissues using HPA and found that the protein expression and antibody staining level of three cases of breast cancer were moderate." (PMID 32528869, 2020). "However, the exact function of SIRT7 in breast cancer progression and metastasis is still lack of experimental evidences." (PMID 28827661, 2017). "In our study, we found SIRT7 expression is significantly decreased in metastatic breast cancers to promote TGF-β signaling activation, which might be a suitable strategy to operate TGF-β signal during breast cancer progression." (PMID 28827661, 2017).
hepatocellular carcinoma (34 papers, 2015 to 2025). A malignant tumor that arises from hepatocytes. "SIRT7, a deacetylase implicated in a variety of malignancies, has been found to play a pro-tumorigenic role in hepatocellular carcinoma, and notably, SIRT7 expression was also upregulated in CSCC." (PMID 40672756, 2025). "Within the realm of tumor-associated disorders, elevated levels of SIRT7 are linked to poor survival outcomes in patients diagnosed with hepatocellular carcinoma." (PMID 40884727, 2025). "In response to IFNγ, SIRT7-deficient hepatocellular carcinoma cells increased MEF2D acetylation levels and consequently PD-L1 levels." (PMID 35585284, 2022). "In other research, high expressions of SIRT7 and H3K18Ac in hepatocellular carcinoma (HCC) were associated with worse patient overall survival (OS), and H3K18Ac levels turned out to be an independent prognostic factor in multivariate analysis." (PMID 31121824, 2019). "SIRT7 is also associated with poor prognosis in gastric, lung, cervical and hepatocellular carcinoma." (PMID 29100388, 2017). "At the same time, activation of SIRT7 super enhancer was found in all samples in hepatocellular carcinoma, and it was found that SIRT7 and methyltransferase EZH2 were co expressed and bound in hepatocellular carcinoma." (PMID 39838405, 2025). "A previous study suggested that SIRT7 promoted the deacetylation of USP39 in hepatocellular carcinoma cells." (PMID 37957720, 2023). "In hepatoma cells, depletion of SIRT7 SE induces H3K18 acetylation and reactivation of key metabolic and immune regulators, leading to significant suppression of tumorigenicity in vitro and in vivo." (PMID 36726725, 2023). "Accumulating evidence has revealed that SIRT7 exerts oncogenic effect in various malignancies including prostate cancer, hepatocellular carcinoma, and cholangiocarcinoma." (PMID 37957720, 2023). "A previous study reported that SIRT7 formed a complex with MEF2D that suppressed PD-L1 expression in hepatocellular carcinoma, which was different from our present study that SIRT7 facilitated PD-L1 expression under ER stress in melanoma." (PMID 36918544, 2023). "In particular, SIRT7 disruption enhanced the efficacy of PD-1 blockade therapy in hepatocellular carcinoma cells." (PMID 38116009, 2023). "In hepatocellular carcinoma, SIRT7 is overexpressed due to transcriptional repression of miR-125a-5p, miR-125b and miR-526b through promoter methylation and also due to overexpression of circPVT1 which sponges miR-3666." (PMID 35585284, 2022). "In the development of hepatoma cells, SIRT7 can deacetylate USP39, which improves the stability of USP39 and promotes the proliferation of HCC." (PMID 35875077, 2022). "Sirt7 knockout hepatocellular carcinoma cells expressed higher levels of PD-L1 by inhibiting the deacetylation of MEDF2D and reduced T cell infiltration and activation." (PMID 34880761, 2021). "Elevated expression of SIRT7 is frequently observed in many cancer types including epithelial prostate carcinomas, hepatocellular carcinoma, colorectal cancer, and lung cancer, and high SIRT7 levels are associated with poor prognosis." (PMID 35174171, 2021). "MiR-125a expression is downregulated in several tumors, including hepatocellular carcinoma (HCC) where it targets sirtuin-7, matrix metalloproteinase-11, VEGF-A, Zbtb7a, and c-Raf." (PMID 28878257, 2017). "In this regard, SIRT7 is found to be an oncogene in hepatocellular carcinoma, gastric cancer and colorectal cancer, and depletion of SIRT7 suppresses tumor growth." (PMID 27916001, 2016). "Several studies have shown that SIRT7 is up-regulated in tumours including breast, thyroid and hepatocellular carcinoma." (PMID 26121130, 2015).
hepatocellular carcinoma (continued). "Numerous studies have found that SIRT7 is typically highly expressed in various human malignancies, including breast cancer, clear cell renal cell carcinoma, lung adenocarcinoma, prostate adenocarcinoma, hepatocellular carcinoma, and gastric cancer." (PMID 40165597, 2025). "Moreover, circRNA–PVT1 silencing has been suggested to suppress sirtuin 7 by increasing miR‐3666 expression, eventually inhibiting hepatocellular carcinoma (HCC) cells in proliferation and metastasis." (PMID 39239069, 2024). "SIRT7 promotes hepatocellular carcinoma development via deacetylation of USP39." (PMID 37957720, 2023). "Moreover, Sirt7 inhibition combined with PD1 blocking therapy can significantly improve the efficacy of hepatocellular carcinoma." (PMID 34880761, 2021). "SIRT7 may promote oncogenesis, tumor growth, and metastasis in gastric cancer and hepatocellular carcinoma." (PMID 32019578, 2020). "Strategies to manipulate the activity of SIRT7 may improve the efficacy of immune therapies for hepatocellular carcinoma." (PMID 31817470, 2019). "In hepatocellular carcinoma (HCC), SIRT7 directly deacetylates the transcription factor myocyte enhancer factor 2D (MEF2D), thereby reducing its transcriptional activity and suppressing PD-L1 expression." (PMID 41471367, 2025). "Therefore, C/EBPα could inhibit SIRT7-expression in hepatocellular carcinoma cells, yet activate SIRT7-expression in hematopoietic cells." (PMID 32214204, 2020). "In hepatocellular carcinoma (HCC), downregulation of miR‐125a‐5p and miR‐125b leads to increased SIRT7 expression, promoting cancer cell proliferation; similar regulatory pathways have been reported in bladder and colorectal cancer." (PMID 40165597, 2025). "Inhibition of SIRT7 reversed MST1 levels and inhibited hepatocellular carcinoma (HCC) growth, demonstrating the SIRT7–MST1–YAP axis as a target." (PMID 41425553, 2025). "Also, SIRT7 expression level is found heightened in a large number of patients with human hepatocellular carcinoma (HCC), and knockdown of SIRT7 repressed growth in liver cancer cells." (PMID 25907989, 2015). "Moreover, SIRT7 has been demonstrated to deacetylate USP39, increasing the stability, and promoting the oncogenic activity of USP39 in hepatocellular carcinoma development." (PMID 37957720, 2023). "Recent research demonstrated that SIRT7 can inhibit the expression of PD-L1 though reducing acetylation of MEF2D in hepatocellular carcinoma cells not exposed to interferon gamma." (PMID 31817470, 2019). "Finally, SIRT7 inhibited the expression of PD-L1 by forming a complex with MEF2D, suggesting that strategies to modulate the activity of SIRT7 may potentially enhance the efficacy of immunotherapies in hepatocellular carcinoma." (PMID 38116009, 2023).
prostate carcinoma (21 papers, 2015 to 2025). A carcinoma that arises from epithelial cells of the prostate gland. "In this study, SIRT7 was found elevated in the advanced stages of prostate cancer and Sirt7 amplification was associated with metastasis and poor prognosis." (PMID 29100388, 2017). "The sirtuin 7 (SIRT7) has been linked to tumorogenesis but its role in prostate cancer is poorly documented." (PMID 29100388, 2017). "Interestingly, the expression of the mutated form restored the wild-type phenotype, suggesting that the deacetylase activity of SIRT7 is implicated in the aggressiveness of prostate cancer cells." (PMID 29100388, 2017). "Furthermore, loss of SIRT7 expression in prostate carcinoma cell lines caused a reversal of the EMT phenotype with upregulation of E‐cadherin and decreased vimentin and Slug expression." (PMID 28994177, 2017). "Indeed, the knockdown of SIRT7 led to the inhibition of the migration by 48% and 68 % in DU145 and PC3 respectively, suggesting that SIRT7 was implicated in prostate cancer cell migration and may participate in PCa aggressive phenotype." (PMID 29100388, 2017). "We found that high SIRT7 expression is correlated with poor prognosis in prostate cancer (PCa) patients." (PMID 40165597, 2025). "In a manner reminiscent of its function in other cancer types, SIRT7 has risen to prominence as a key influencer in propelling the advancement of prostate cancer (PCa)." (PMID 38383727, 2024). "For example, SIRT7 promotes the proliferation and androgen-induced autophagy in prostate cancer via the AR signaling." (PMID 37957720, 2023). "SIRT7 is responsible for the aggressive behavior of prostate cancer cells, and its downregulation suppresses migration and invasion of cancer cells." (PMID 35317831, 2022). "In prostate cancer cells, SIRT7 undergoes upregulation to inhibit SMAD4, leading to activation of AR signaling, subsequent induction of autophagy and enhancing cancer progression." (PMID 35317831, 2022). "Taken together, these findings indicate that SIRT7 expression promotes the proliferation, metastasis, and androgen-induced autophagy of prostate cancer via induction of AR signaling." (PMID 36291902, 2022). "SIRT7 is overexpressed in various human cancers, including prostate cancer, suggesting a pivotal role of SIRT7 in the progression of prostate cancer." (PMID 36291902, 2022). "In prostate cancer cells, SIRT7 cooperates with SIRT1 to suppress E-cadherin regulatory genes to promote EMT, and high SIRT7 levels are associated with metastatic disease and poor prognosis." (PMID 35174171, 2021). "In contrast, SIRT7 was found to promote mesenchymal transition in the context of oncogenic roles of SIRT7 in colorectal and prostate cancers, primarily by suppressing E-Cadherin expression." (PMID 32656073, 2020). "We established that SIRT7 promoted prostate cancer proliferation, autophagy and metastasis via the AR signaling pathway indirectly." (PMID 32019578, 2020). "Although only a few studies investigated the relationship between sirtuins and EMT, SIRT7 depletion in PC3 prostate cancer cell line was shown to impair migration and invasiveness, reprograming neoplastic cells towards epithelial gene expression." (PMID 32344886, 2020). "Remarkably, previous reports on SIRT7 in uterus, colon, kidney, ovary and prostate cancers revealed increased expression levels." (PMID 32344886, 2020). "It has been demonstrated that SIRT7 plays a vital role in the aggressiveness of prostate cancer, meaning it is a promising predictive marker for aggressive prostate cancer." (PMID 31121824, 2019). "SIRT7 interacts with SIRT1 to enhance SIRT1-dependent prostate cancer cell metastatic properties and promotes E-cadherin transcriptional repression." (PMID 30510540, 2018). "As shown in prostate cancer, SIRT7 binds and maintains the deacetylated state of H3K18 at the promoters of many tumor suppressor genes by interacting with the ELK4 transcription factor." (PMID 30510540, 2018).
prostate carcinoma (continued). "In SIRT7-deficient cells, E-cadherin and DAB2 interacting protein (DAB2IP; a tumor suppressor gene, whose loss promotes EMT and metastasis in prostate cancer) are significantly increased in mRNA level." (PMID 30510540, 2018). "Aggressiveness is associated with resistance to chemotherapy, thus, we assessed the implication of SIRT7 in the sensitivity to Docetaxel, the major chemotherapeutic agent for the treatment of prostate cancer." (PMID 29100388, 2017). "To study the potential role of SIRT7 in prostate cancer cell viability and aggressiveness, we downregulated the expression of SIRT7 in DU145 and PC3 cells, using two siRNA targeting two different regions of SIRT7." (PMID 29100388, 2017). "Our results demonstrate that SIRT7 promotes prostate cancer cell aggressiveness and chemoresistance and suggest that SIRT7 is a good predictive biomarker of PCa aggressiveness." (PMID 29100388, 2017). "In conclusion, our study demonstrates that SIRT7 is a new promising marker for aggressive prostate cancer." (PMID 29100388, 2017). "To determine if there is a direct relationship between the level of SIRT7 and PCa cell aggressiveness, we overexpressed SIRT7 in the poorly aggressive, androgen-dependent human prostate cancer cell line LNCaP." (PMID 29100388, 2017). "Given that we found SIRT7 destabilized SMAD4, it indirectly supports the notion that higher expression of SIRT7 promoted prostate cancer metastasis." (PMID 28827661, 2017). "SIRT7-depletion substantiallyimpaired migration of the metastatic prostate cancer cell line PC3, reducing thehealing percentage by ~40% compared to control cells." (PMID 25923013, 2015). "Regulatory factors and potential mechanisms of SIRT7 in prostate cancer." (PMID 40165597, 2025). "They further demonstrated that SIRT7 expression is positively correlated with AR signaling in both prostate cancer tissues and cells (LNCaP and 22Rv1) and that SIRT7 knockdown upregulates SMAD4, a tumor suppressor protein, which interacts with AR to control its signaling in prostate cancer." (PMID 36291902, 2022). "SIRT7 plays an important role in the development and progression of human PCa and may be a promising prognostic marker for prostate cancer." (PMID 32019578, 2020). "The knock down of SIRT7 inhibits the migration of two androgen-independent prostate cancer cells (DU145 and PC3), although the overexpression of the native protein, but not the mutated form, promotes cell migration and invasion of the poorly aggressive, androgen-dependent LNCaP cell line." (PMID 31121824, 2019). "Hypoacetylation of H3AcK18 is associated to prostate carcinoma with poor prognosis, and increase of H3AcK18 caused by absence of SIRT7 at sites of DNA damage affects the maintenance of genome integrity." (PMID 29632619, 2018). "SIRT7 expression has been found to correlate inversely with E‐cadherin in prostate cancer." (PMID 28994177, 2017). "We have demonstrated that SIRT7 plays an important role in the aggressiveness of prostate cancer." (PMID 29100388, 2017). "Overall, these findings indicate that SIRT7 overexpression induces EMT to promote the aggressiveness of both androgen-dependent (LNCaP) and androgen-independent (DU145) prostate cancer cells." (PMID 36291902, 2022). "Taken together, these findings indicate that SIRT7 promotes the migration and metastasis of PC3 prostate cancer cells by upregulating EMT." (PMID 36291902, 2022). "In accordance with a role of SIRT7 in prostate cancer progression, we showed that the knockdown of SIRT7 decreased cancer cell migration but did not alter cell viability." (PMID 29100388, 2017).